MYH14 (myosin heavy chain 14)
Diseases named in the same sentence as MYH14 in open-access papers:
MYH14 is named in the same sentence as 39 diseases in open-access papers, as found by Europe PMC text mining. Sharing a sentence is not in itself a finding about the gene and the disease. The quoted sentences say what the papers report.
deafness (14 papers, 2009 to 2025). An inherited or acquired condition characterized by the complete loss of the ability to hear from one or both ears. "After applying a filtering strategy using GEM.app followed by validation and segregation analysis of the variants in the family, we identified new deafness causative mutations in the MYH14 and WFS1 genes in part B and C of the composite family, respectively." (PMID 25289672, 2014). "Rather, we found a potentially pathogenic variant (c.G5054A:p.R1685Q) in the MYH14 gene, a known deafness gene in DFNA4 locus from this proband." (PMID 23990876, 2013). "Although mutation in MYH14 can cause DFNA4, there are reports suggesting that another unidentified gene is also involved in this type of deafness." (PMID 19320974, 2009). "Similarly, a late-aged female (S.10) with a MYH14 variant (chr19:50760672, NM_024729.3:c.2038C>T, p.Arg680Cys) had a late onset complex disease with features of myopathy, neuropathy and deafness." (PMID 34103343, 2021). "The MYH14 gene was identified as a causal gene of DFNA4 deafness." (PMID 25289672, 2014). "These disease associations of dysregulated proteins for instance include lipodystrophy (PLN1), deafness (MYH14) and peripheral neuropathy with myopathy, hoarseness and hearing loss (MYH14)." (PMID 40721798, 2025). "Twenty-five genes were present in both male and female hearing difficulty high variant load lists, including seven deafness genes (CLIC5, MYH14, COL9A3, ELMO3, FSCN2, GJB2, SLC26A5)." (PMID 35761239, 2022). "The variants of TMC1, ESPN, POU3F4, MYH14, EYA1, and MR-RNR1 genes followed those from the top tier deafness genes in the order of frequency as a molecular etiology of severe-to-profound NSHL in Vietnamese." (PMID 30733538, 2019). "In the future, this approach may be used to test the feasibility of treating other inherited deafness cases in which the SV is the predominant site affected (e.g. mutations in KCNE1, CCDC50, DFNA5, MYH14, TFCP2L3, TMPRSS3 genes)." (PMID 26084842, 2015). "Mutations in non-muscle myosins MYH9, MYH14 and myosin VIIa have been implicated in deafness in mammals." (PMID 21888654, 2011).
hearing loss (14 papers, 2016 to 2025). "MYH14-associated hearing loss is rare, the currently available information regarding the variant spectrum and clinical characteristics being limited." (PMID 36743950, 2023). "The clinical information revealed by the present study will contribute to further diagnosis and management of MYH14-associated hearing loss." (PMID 34681017, 2021). "In this study, genetic screening for MYH14 variants was carried out using a large series of Japanese hearing-loss patients to reveal more detailed information." (PMID 34681017, 2021). "Further evidence also shows that MYH14 is a candidate noise-induced hearing loss (NIHL) susceptible gene." (PMID 28101381, 2016). "This is the largest cohort studied for MYH14-associated hearing loss to date." (PMID 34681017, 2021). "However, the physiological link between MYH14 mutations and sensorineural hearing loss is still unclear." (PMID 32711451, 2020). "Inhibition of the MYH14 gene can lead to defects in extension of the cochlear duct, which may be the physiological mechanism of hearing impairment in subjects who carry MYH14 gene mutations." (PMID 32711451, 2020). "Two genes encoding conventional myosins, MYH9 and MYH14, and four genes encoding unconventional myosins, MYO3A, MYO6, MYO7A and MYO15A, are associated with nonsyndromic hereditary hearing loss in human." (PMID 38562617, 2024). "Variants in MYH14 are reported to cause autosomal dominant nonsyndromic hereditary hearing loss (ADNSHL), with 34 variants reported to cause hearing loss in various ethnic groups." (PMID 34681017, 2021). "Myosin genes are known to be responsible for 10 types of syndromic as well as non‐syndromic hearing loss (MYO7A, DFNA11/DFNB2/USH1B; MYH9, DFNA17; MYH14, DFNA4; MYO6, DFNA22/DFNB37, MYO3A, DFNB30; MYO15A, DFNB3)." (PMID 32027099, 2020). "Along with these homozygous mutations, we detected two heterozygous variants in well described hearing loss genes (MYO7A and MYH14)." (PMID 31898538, 2020). "To date, missense and nonsense variants of the MYH14 gene have been reported in families with mild to severe degrees of AD SNHL, which usually manifests with milder hearing loss and later onset than AR inherited hearing loss." (PMID 32711451, 2020). "Actually, only one case has been reported with IPN and hearing loss, and two articles have been published about hearing loss with the same pathogenic variants.We can wonder whether a founder effect exists, or if a pathogenic variant in a HL gene close to MYH14 exists." (PMID 31393079, 2019). "In some case reports, MYH14 mutations in patients are associated with hearing loss and MYH10 mutations with microcephaly, developmental delay, hydrocephalus, cerebral and cerebellar atrophy, and hearing loss." (PMID 40464565, 2025). "Mutations in non-muscle myosin gene MYH14 appear to be associated with hearing loss rather than muscle defects, although it has also been recently linked to mitochondrial fission defects." (PMID 36282542, 2023). "As a consequence, hearing loss in that population could be due to other genes, as we started to point out for two of our patients, with a pathogenic variant in COCH and a suspected one in MYH14." (PMID 31393079, 2019).
cardiac hypertrophy (4 papers, 2016 to 2025). "Our study implicated Klf4 and Myh14 to be negative regulators of cardiac hypertrophy under ISO stress." (PMID 27385019, 2016). "Collectively, these prior studies implicated Klf4 and Myh14 as negative regulators of stress-induced cardiac hypertrophy in vivo, which is also supported by our results." (PMID 27385019, 2016). "Further understanding of the crosstalk between Myh14, β-catenin, and Foxo1, will likely reveal important mechanisms regarding how Myh14 deficiency leads to cardiac hypertrophy under ISO stress." (PMID 27385019, 2016). "Myh14 was the only gene expressed in the heart that was located at the chromosome 7 locus affecting cardiac hypertrophy in our study." (PMID 27385019, 2016). "These seemingly discrepant results raise important questions regarding the mechanisms through which Myh14 deficiency leads to cardiomyocyte death in the absence of mechanotransduction stress in vitro and cardiac hypertrophy on an organ level in vivo." (PMID 27385019, 2016). "The expression of Myh14, a marker of isoproterenol‐mediated hypertrophy, and the transcription factor SRF, a known mediator of cardiac hypertrophy, was significantly increased in Iso‐treated cardiomyocytes as well as in the cardiomyocytes of old animals." (PMID 40538075, 2025). "Network analysis mapping protein–protein interactions and synergistic actions of AR using multi-component networks reveal drug targets such as ACADM, COX4I1, COX6B1, HBB, MYH14, and SLC25A4, as potential pharmacological co-targets for cardiac hypertrophy." (PMID 33589646, 2021).
autosomal dominant nonsyndromic hearing loss (3 papers, 2012 to 2024). Autosomal dominant form of nonsyndromic deafness. "MYH9 and MYH14 are identified as chromosomal loci of autosomal dominant nonsyndromic hearing loss, DFNA17 and DFNA4A, respectively." (PMID 38562617, 2024). "In our study, we examined a four-generation Han Chinese family presenting with autosomal dominant nonsyndromic deafness and identified a novel missense mutation, c.5417C > A (p.A1806D), in the MYH14 gene by using targeted gene capture and Sanger sequencing." (PMID 32711451, 2020). "Currently, variants of MYH9 and MYH14 genes are associated with autosomal dominant nonsyndromic hearing loss, DFNA17 and DFNA4A, respectively." (PMID 38562617, 2024).
colon carcinoma (2 papers, 2008 to 2021). "CRC cells express three NM II paralogs, NM IIA, NM IIB and NM IIC, encoded by different genes (MYH9, MYH10 and MYH14, respectively); however, the literature to date is limited to examining NM IIA expression in colon cancer." (PMID 33670106, 2021).
E. coli infection (2 papers, 2023 to 2024). "Few targeted genes in humans like LCP2, GABRA6, and MYH14 were predicted to be associated with disease pathways of Yesinia infection (hsa05135), neuroactive ligand-receptor interaction (hsa04080), and pathogenic Escherichia coli infection (hsa05130), respectively." (PMID 38674383, 2024).
myotonic dystrophy type 1 (2 papers, 2014 to 2024). Steinert disease, also known as myotonic dystrophy type 1, is a muscle disease characterized by myotonia and by multiorgan damage that combines various degrees of muscle weakness, arrhythmia and/or cardiac conduction disorders, cataract, endocrine damage, sleep disorders and baldness. "The precise splicing pattern of MYH14 observed in TIRM− samples compared to controls is also observed in Myotonic Dystrophy type 1 (DM1), a repeat expansion myopathy with associated sensorineural deafness." (PMID 37856562, 2024). "In addition, patients expressing aberrant splicing products of MYH14 develop myotonic dystrophy type 1 (DM1), a progressive multisystem genetic disorder that affects 1 in 8000 people worldwide." (PMID 25072053, 2014).
neuropathy (2 papers, 2021). A disorder affecting the nervous system that manifests with pain, tingling, numbness, and/or muscle weakness. "An autosomal dominant mutation in the protein MYH14 leads to neuropathy, myopathy, hoarseness, and hearing loss." (PMID 33589646, 2021).
Obesity (2 papers, 2016 to 2020). Accumulation of substantial excess body fat. "From the GWAS, the significant markers associated with obesity-related traits including body weight (CACNA1B, C22orf39, U6, MYH14, PTPN2, SEH1L) and blood sugar (PRSS55, GRIK2), were identified." (PMID 33182249, 2020).
pancreatic cancer (2 papers, 2023 to 2024). "MYH9 and MYH14 were highly expressed, while MYH10 was under-expressed in pancreatic cancer compared to adjacent normal tissues." (PMID 37679666, 2023).
atrial fibrillation (1 paper, 2021). A disorder characterized by an electrocardiographic finding of a supraventricular arrhythmia characterized by the replacement of consistent P waves by rapid oscillations or fibrillatory waves that vary in size, shape and timing and are accompanied by an irregular ventricular response. "Novel variants in DCTN1, MYH14, and RBM20 were identified in Family 1 with cardiac and limb-girdle muscle involvement and in TRIM63, ACTC1, and TTN in the proband of family 2 with a distal lower limb phenotype and atrial fibrillation." (PMID 33170376, 2021).
autosomal dominant nonsyndromic deafness-4A (1 paper, 2020). "It has been reported that mutations in MYH14 can result in autosomal dominant nonsyndromic deafness-4A (DFNA4)." (PMID 32711451, 2020).
diabetes (1 paper, 2020). "However, a role for MYH14 in diabetes or neurodegenerative diseases is not reported." (PMID 32041280, 2020).
gastric cancer (1 paper, 2023). A primary or metastatic malignant neoplasm involving the stomach. "Finally, we identified a gene set associated with the differentiation status of gastric cancer, including AGR3, CLDN3, CLDN4, FABP1, LGALS4, PHGR1, MYH14 and S100A14." (PMID 36729271, 2023).
kidney damage (1 paper, 2024). "We confirmed the influence of several known NEMG on kidney disease and function and found novel associations for SLC39A13, CFL1, ACP2 or ATP5G1 with serum variables and kidney damage, and for SLC4A1, NUP210 and MYH14 with ESKD." (PMID 38858654, 2024).
lumbar disc degeneration (1 paper, 2016). "Interestingly, a suggestive association was reported for rs4802666 of MYH14 (19q13.33) in a GWAS meta-analysis of lumbar disc degeneration." (PMID 27764105, 2016).
macular degeneration (1 paper, 2022). Loss of vision in the central portion of the retina (macula), secondary to retinal degeneration. "One non-USH proband exhibited variants in different genes underlying HI (MYH14) and retinal or macular degeneration (FBN2)." (PMID 34148116, 2022).
Myocardial fibrosis (1 paper, 2016). "Histological sections of Myh14-/- hearts revealed no abnormal phenotype at baseline but increased myocardial fibrosis and intercalated disc disarray after ISO treatment." (PMID 27385019, 2016).
neuroblastoma (1 paper, 2020). Neuroblastoma (NB) is the most common solid, extracranial childhood tumor. "MYH14 could be suppressing tumor progression in high-risk neuroblastoma." (PMID 33245713, 2020).
respiratory failure (1 paper, 2022). The significant impairment of gas exchange within the lungs resulting in hypoxia, hypercarbia, or both, to the extent that organ tissue perfusion is severely compromised. "Hence, alterations in the MYH14 function may thereby increasing the severity of respiratory failure in COVID-19 infection." (PMID 35328087, 2022).
sensorineural hearing loss (1 paper, 2020). "MYH14 gene mutations have been suggested to be associated with nonsyndromic/syndromic sensorineural hearing loss." (PMID 32711451, 2020).
Tinnitus (1 paper, 2021). Tinnitus is an auditory perception that can be described as the experience of sound, in the ear or in the head, in the absence of external acoustic stimulation. "A recently published GWAS reported that rs1377817, a SNP intronic to MYH14, was associated with a high residual serum platinum level and possibly correlated to the development of several cisplatin-related toxicities such as tinnitus and Raynaud’s phenomenon." (PMID 34834585, 2021).
type 2 diabetes (1 paper, 2022). "Non-synonymous variants in MYH14 increase risk of neurological progression of type 2 diabetes and peripheral neuropathy." (PMID 35328087, 2022).
myopathy (6 papers, 2019 to 2025). A disease of the muscle in which the muscle fibers do not function properly. "Mutations in the MYH14 gene can result in peripheral neuropathy, hoarseness, myopathy, and hearing loss." (PMID 32711451, 2020). "The MYH14 gene was reported to be related to peripheral neuropathy, myopathy, hoarseness and hearing loss (PNMHH), and the MYH14 protein is expressed widely within cochlear tissues, such as the organ of Corti, spiral prominence epithelium, stria vascularis, and cochlear duct." (PMID 32711451, 2020). "Next, MYH14-Mant-ADP (DrugBank Id: DB03126) complex helps in Microfilament motor activity that has a major role in myopathy and cytokinesis." (PMID 33589646, 2021).
peripheral neuropathy (6 papers, 2020 to 2025). A disorder affecting the peripheral nervous system. "However, the example of MYH14 is especially interesting, given the possibility the impairing fission only at the cell extremity may be sufficient to cause peripheral neuropathy." (PMID 33810506, 2021). "Intriguingly, pathogenic variants in many of the peripheral neuropathy proteins discussed here lead to hyperfused mitochondrial networks (e.g., SLC25A46, DRP1, MFF, GDAP1, MYH14)." (PMID 33810506, 2021). "For example, while the MYH14 general upregulation did not make obvious sense for muscle defects since it is not part of the contractile machinery, it has been shown that a mutation in MYH14 disrupts mitochondrial fission in peripheral neuropathy." (PMID 36282542, 2023).
tumor (6 papers, 2015 to 2024). "MYH14 encodes a protein related to muscle contraction, potentially impacting tumor cell migration and invasion by regulating cytoskeletal remodeling and movement during the migration process." (PMID 38928496, 2024). "The protein encoded by MYH14 is highly expressed in normal kidney tissues, mainly located in the cell membrane and cytoplasm of renal tubules, whereas it is lowly expressed in tumor tissues, mainly located in the cytoplasmic and membranous regions." (PMID 38928496, 2024). "MYH9 and MYH10 mutations were identified at a similar frequency in 4–5% of cases, and MYH14 was mutated in 2 tumors, and these mutations tended to be mutually exclusive except in one tumor where co-occurrence of MYH9 and 10 mutations was observed." (PMID 26369831, 2015). "A drug 4-hydroxyacetophenone (4-HAP) has been synthesized to increase cortical tension of tumor cells and decrease cell deformability by enhancing the cortical localization of myosin IIC (MYH14)." (PMID 37864030, 2023). "It is speculated that MYH14 and SLC6A19 may be involved in the dynamic development of tumor stem cells through epigenetic mechanisms, as observed in our study." (PMID 38928496, 2024). "Several of the remaining 21 genes not in the GS, such as MYH14, MED23, and ZFP36L1 in BRCA, and ZNF292, FUBP1, and DTX1 in CLL, had also been implicated in tumor development." (PMID 29030609, 2017). "Considering the findings that MYH14 and SLC6A19 can impact TME progression through epigenetic regulation, targeting these signaling pathways may offer a dual strategy to disrupt the dynamics of tumor stem cells and epigenetic regulation within the TME, thereby delaying tumor progression." (PMID 38928496, 2024).
cancer (2 papers, 2023 to 2024). A tumor composed of atypical neoplastic, often pleomorphic cells that invade other tissues. "Because sesamolin was shown to have superior anti-cancer properties than its metabolite sesamol, we investigated whether sesamolin or its metabolite sesamol could target MYH14." (PMID 38698330, 2024).
genetic diseases (1 paper, 2020). "The findings broadened the phenotype spectrum of MYH14 and highlighted the combined application of gene capture and Sanger sequencing is an efficient approach to screen pathogenic variants associated with genetic diseases." (PMID 32711451, 2020).
MYH14 also shares sentences with these, for which no sentence is quoted: Hearing impairment (2 papers); autosomal recessive deafness (1); endometrial cancer (1); hearing disorder (1); Hip dysplasia (1); infection (1); kidney disease (1); lipodystrophy (1); Marfan syndrome (1); neurodegenerative disease (1); prostate carcinoma (1).